TRIM45 (tripartite motif containing 45)
Diseases named in the same sentence as TRIM45 in open-access papers (continued):
Sharing a sentence is not in itself a finding about the gene and the disease.
tumor (12 papers, 2017 to 2024). "It has been reported that TRIM45 is associated with tumours and inflammatory diseases." (PMID 38037161, 2023). "The results of ANKRD52 level expressed that the HOXC10, KNOP1, and TRIM45 in the tumor tissue were higher in the paracancerous tissue, and the opposite was true for SGPP1." (PMID 37521466, 2023). "In this study, we found that the expression of TRIM45 in tumor tissues is higher than that in normal tissues, which correlated with a better prognosis." (PMID 37521466, 2023). "The expression of TRIM45 is an independent prognosis factor from patient age, tumor stages, and molecular subtypes." (PMID 35928444, 2022). "Overexpression and knockdown experiments in GBM cell lines and xenograft models suggested a tumor suppressive role of TRIM45, as its expression attenuated GBM growth." (PMID 36139694, 2022). "Similar results were obtained from immunoblotting experiments, showing the downregulation of TRIM45 protein expression in tumor tissues." (PMID 28542145, 2017). "In brief, through the analysis, we provided several TRIMs that may contribute to the tumor progression and TRIM45 as a potential new prognostic biomarker for BC." (PMID 35928444, 2022). "Consistently, TRIM45 was recently identified as a tumor suppressor in the brain." (PMID 32290274, 2020). "TRIM45 expression levels are also inversely correlated with tumor grades, as HGGs (Grade III/IV) were reported to exhibit significant lower levels of TRIM45 than LGGs (Grade I/II)." (PMID 36139694, 2022). "The difference analysis of 41 paired samples of TCGA-COAD showed that the mRNA levels of ARHGAP4, SIAH2, TRIM45, and WDR72 were significantly upregulated in the tumor group, while MID2 and UBE2D2 showed no statistical difference." (PMID 39268080, 2024). "TRIM45 had been previously shown to negatively regulate the MAPK and NFκB pathway, but its role as tumor suppressor had not been explored in GBM." (PMID 33324551, 2020).
cancer (6 papers, 2015 to 2025). A tumor composed of atypical neoplastic, often pleomorphic cells that invade other tissues. "It has been reported that the B-box domain of TRIM45 is important for the interaction with receptor for activated C kinase 1 (RACK1) in cancer cells." (PMID 40593126, 2025). "We focused on ADAT2, CCNL2, DBF4B, and TRIM45 mRNAs that played key roles in cancer biology to demonstrate that alteration of their translational efficiency occurred via a BRCA1-dependent mechanism in cultured cells and in patient tumors." (PMID 32290274, 2020). "For example, the TRIM45 gene encodes a protein to regulate the MAPK and NF-κB pathways which may inhibit the cancer cell proliferation." (PMID 34168979, 2021).
infection (2 papers, 2022 to 2025). The state of being infected such as from the introduction of a foreign agent such as serum, vaccine, antigenic substance or organism. "We next performed the Co-IP experiment in HEK293T cells that were first transfected to express V5-tagged TRIM45 for 24 h, followed by infection with WSN (H1N1), AH05 (H5N1) or AH13 (H7N9) virus (MOI = 5) for 12 h." (PMID 41129599, 2025). "We found that TRIM45 also interacted with PB2 in the course of infection with these viruses." (PMID 41129599, 2025). "To further verify that TRIM45 mediates the inflammatory response associated with the NF-κB signaling pathway, we pretreated microglial cells with 100 μM PDTC, an inhibitor of the NF-κB signaling pathway, for 1 h after infection with LV-TRIM45 for 48 h and then subjected them to OGD/R." (PMID 35217833, 2022). "The TRIM45-overexpressing cells were infected with A/WSN/1933 (WSN, H1N1), A/Anhui/2/2005 (AH05, H5N1), or A/Anhui/1/2013 (AH13, H7N9), and at 24 and 48 h post-infection (p.i.), the culture supernatant was titrated for infectious viruses." (PMID 41129599, 2025).
TRIM45 also shares sentences with these, for which no sentence is quoted: CNS tumors (1 paper); colitis (1); H1N1) virus infection (1); memory impairment (1); non-small cell lung carcinoma (1).